NOTCH2 (notch receptor 2)
Diseases named in the same sentence as NOTCH2 in open-access papers (continued):
Sharing a sentence is not in itself a finding about the gene and the disease.
tumor (continued). "In the present study, GC evolution induced elevations of Notch1 and Notch2 in both peripheral bloods and tumor tissues, indicating that Notch signaling might take part in GC progression." (PMID 30988066, 2019). "Notch2 can play a different role in TNBCs, thus acting as an oncogene or tumor suppressor." (PMID 31379945, 2019). "Thus, we firstly screened Notch1 and Notch2 mRNA expressions in tumor and peritumor tissues which were obtained during gastroscopic biopsy in 24 of GC patients (7 of TNM stage I, 6 of stage II, 6 of stage III, and 5 of stage IV)." (PMID 30988066, 2019). "In addition, the authors demonstrated an opposite expression of Notch1 and Notch2 proteins during tumor development, related to its differentiation state." (PMID 31379945, 2019). "Similarly, in agreement with the existing literature, we found that NOTCH2 was deleted in CC (preferentially in splenic flexure tumors), which suggested a role as tumor suppressor in this subset of CC." (PMID 29755661, 2018). "On the other hand, several studies reported that high NOTCH1 and NOTCH2 expression with early tumor stages might indicate a tumor-suppressive role of NOTCH signaling in gastric cancer." (PMID 29665790, 2018). "In this study, ACGs was administered in GC cells to detect the cellular process affected by this compound and whether it played a tumor suppressor role through the regulation of Notch2." (PMID 28416750, 2017). "Notch1, Notch2 and Notch4 mRNA expression levels were similar in AtT20 cells and normal adult pituitaries whereas Notch3 mRNA expression was reduced in corticotrope tumor cells in relation to normal mouse pituitary cells." (PMID 28915655, 2017). "NOTCH2 expression was decreased in CRC and was associated with tumor differentiation." (PMID 27938406, 2016). "The detailed mechanisms of Notch2 have been studied and reported in several tumours." (PMID 27158037, 2016). "As a target gene of miR-10735, miR-204-5p10 and miR-23b13, Notch2 may also regulate cell migration and tumour invasion." (PMID 27158037, 2016). "Interestingly, Notch2 induction accelerated tumor malignancy along with increased mesenchymal markers, indicating that Notch2 is necessary and sufficient for the loss of E-cadherin and increased N-cadherin and vimentin levels." (PMID 27462787, 2016). "Above results indicate that Notch2 seems to be a tumor oncogene in gastric carcinogenesis." (PMID 27363496, 2016). "Contradictorily, tumor suppressive role of NOTCH2 was also reported in one publication." (PMID 27938406, 2016). "Furthermore, genetic ablation of MK delayed tumor formation and reduced tumor incidence in a transgenic neuroblastoma model through attenuation of the Notch2 signaling pathway." (PMID 26798989, 2016). "We observed that tumor-induced decrease in the expression of Notch receptors, Notch1, Notch2, Notch3 and Notch4, as well as ligands Dll1, Dll4 and Jagged1 in splenocytes of 4T1HA and RencaHA tumor-bearing mice could be reversed by treatment with bortezomib." (PMID 26431276, 2015). "Nevertheless, in conclusion and to the best of our knowledge, our study showed for the first time a close relationship of a decrease of NOTCH1 and NOTCH2 expression with tumor progression in GC, and our findings suggested that, in particular, NOTCH1 expression was a marker for good prognosis." (PMID 25954607, 2015). "To further determine whether C8orf4 inhibits the NOTCH2 signalling in the propagation of xenograft tumours, we examined the distribution of N2ICD and NOTCH2 target gene activation in C8orf4-deficient xenograft tumour tissues." (PMID 25985737, 2015).
tumor (continued). "The close relationship of high NOTCH1 and NOTCH2 expression with early tumor stages may indicate a tumor-suppressive role of NOTCH signaling in GC." (PMID 25954607, 2015). "NOTCH2 signalling is highly activated in HCC tumours and liver CSCs." (PMID 25985737, 2015). "Finally, NOTCH2 depletion in C8orf4-silenced Huh7 cells or HCC primary cells also abrogated the C8orf4 depletion-mediated enhancement of xenograft tumour growth, suggesting that C8orf4 acted as upstream of NOTCH2 signalling." (PMID 25985737, 2015). "The dynamic nature of CSCs or persistent NOTCH2 activation may contribute to the high number of C8orf4−/N2ICDnuc/HEY1+ cells in advanced HCC tumours and correlation in the patient cohort." (PMID 25985737, 2015). "In addition, an increase in NOTCH2 expression in the residual tumor cells compared to the pretherapeutic biopsies was shown, indicating a prominent role of NOTCH2 in chemotherapy resistance in GC." (PMID 25954607, 2015). "Experimental evidence demonstrates that Notch inhibition by either mAb against Notch1 or Notch2 appears to have anti-tumor and anti-angiogenic effects with limited gastrointestinal toxicities while simultaneous inhibition of Notch1 and 2 lead to gastrointestinal toxicity, as seen with many GSIs." (PMID 24959528, 2014). "All the three NOTCH2 mutated cases expressed Notch2, P65 and P50, whereas Notch2 and P65 were both negative in their matched surrounding non-tumor tissues." (PMID 25314575, 2014). "Reverse transcriptase - quantitative PCR (RT-qPCR) was utilized to quantify HES1, HEY1, NOTCH1 and NOTCH2 gene expression in matched tumor and normal metaphyseal bone samples taken from dogs treated for appendicular OSA at the Colorado State University Veterinary Teaching Hospital." (PMID 23816051, 2013). "Irrespective of the mechanism and the true nature of the residual tumour cells expressing NOTCH2, our results may have therapeutic implications." (PMID 22970250, 2012). "Interestingly, tumor cells had similar Notch2 mRNA and protein levels to normal myoblasts, but the latter showed higher Notch2 ICD levels." (PMID 23158439, 2012). "We further investigated the roles of Notch1 and Notch2 in MB tumor biology in which their opposite effects have already been reported: Notch1 activity inhibits cell growth and induces apoptosis, while Notch2 up-regulates Hes1 expression, which promotes cell proliferation." (PMID 21931765, 2011). "However,Notch-2 has also been proposed to have a tumor suppressiveeffect in CRC,suggesting complex, possibly stage related, functions of Notch signaling in theintestine." (PMID 21437251, 2011). "The analysis of the entire NOTCH2 coding sequence was performed in four cases and did not reveal any mutation therefore indicating that NOTCH2 does not harbor genetic characteristics of a tumor suppressor gene." (PMID 19119320, 2009). "In fact, since NOTCH1 can be regarded either as an oncogene or as a tumor suppressor, depending on the cellular context, this rule may also apply to NOTCH2." (PMID 17593975, 2007). "All analyzed GBM without 1p loss (5/5) also had equal copy numbers between NOTCH2 and N2N (tumor G49)." (PMID 17593975, 2007). "Our results suggest NOTCH2 is a viable biomarker for paclitaxel resistance and that combining NOTCH2 inhibitor with taxane is an effective therapeutic strategy to selectively disrupt tumor-macrophage interaction and overcome macrophage-mediated taxane resistance in NOTCH2-positive tumors." (PMID 41519773, 2026). "Considering that NOTCH2 is a tumor-inducing oncogene and indispensable for CLL development in a mouse model, we hypothesize that the induction of a NOTCH2ΔNRR GOF phenotype by somatic recombination has the potential to be an initial malignant hit in a CLL precursor cell." (PMID 39684291, 2024).
tumor (continued). "Research has shown elevated levels of Notch expression in tumor cells compared to the adjacent hepatic parenchyma, with variable distribution in the nucleus and cytoplasm: Notch 1 and 4 are expressed in both the nucleus and the cytoplasm, while Notch 2 and 3 are expressed only in the cytoplasm." (PMID 38927059, 2024). "Furthermore, according to TCGA data, Notch2 was obviously higher in HCC tumor tissues." (PMID 37198207, 2023). "However, in some other cancers, such as SCLC and embryonal brain tumors, NOTCH2 may act as a tumor promotor." (PMID 37728427, 2023). "Altogether these data prompted us to hypothesize that the homophilic N-Cadherin interaction between MDA cells and SNOs is used by tumour cells for engraftment to the endosteal niche, while only a small subpopulation co-expressing Notch2 also acquires the dormant phenotype." (PMID 35267624, 2022). "However, additional studies suggested that while the tumor-suppressor role may reside with Notch 1, Notch 2 acts more like an oncogene, and therefore, targeting Notch 2 may have merit." (PMID 34059639, 2021). "Interestingly, it has been observed that NOTCH1 controls NOTCH2, thus acting as a tumor suppressor." (PMID 34446793, 2021). "Moreover, the notable ability of NAC to suppress cancer cell proliferation and tumor growth suggests that targeting Notch2 may serve as a promising strategy for developing future therapies of GBM, implying a novel application of NAC on GBM therapy." (PMID 30606241, 2019). "We therefore hypothesized that NOTCH2 functions as a tumor suppressor." (PMID 31699119, 2019). "Finally, loss of Notch1 in tumor cells did not affect the protein expression of Notch2, Jag1, and BEC marker Sox9 as well as mRNA levels of Notch targets, including Hes5 and Hey2." (PMID 29545603, 2018). "Indeed, different Notch family members may have tumor supporting and tumor suppressing roles, such as Notch1 and Notch2, respectively." (PMID 29383147, 2017). "Moreover, Notch1 and Notch2 protein levels are decreased in the tumor." (PMID 29206870, 2017). "Moreover, a large scale screening process on a wide range of tumors and tumor subtypes should identify nuclear NOTCH2/CSL positive entities that might respond to gliotoxin treatment." (PMID 28736522, 2017). "It is known that high expression levels of Jagged1, Notch 1 and Notch2 correlate with tumor progression of myeloma;44 in this context, it has been recently proposed an activating role of Notch on IL-6 proliferating signals in the bone marrow niche, which results in an enhancement of tumor growth." (PMID 27929540, 2016). "Moreover, we checked whether miR-23b-mediated inhibition of tumor growth in SC-M1 cells depends on Notch2 pathway." (PMID 26041881, 2015). "Furthermore, low C8orf4 expression in tumour cells results in overall Notch2 activation, which then may have more of a progenitor signature and be more aggressive." (PMID 25985737, 2015). "However, overall, it is apparent that hypoxic gliomaspheres mimic the in-vivo tumor condition better than the other tissue culture model as the upregulation of Notch genes (Notch1, Notch2, Notch3, Dll1, Hes1, Hey1 and Hey2) is further enhanced upon exposure to hypoxia." (PMID 25734817, 2015). "In addition, inhibiting NOTCH2 or Jag1 dramatically reduces tumour burden and growth." (PMID 25985737, 2015). "In addition, the prognostic effect observed might be enhanced by an increase in the expression of NOTCH2 in the residual tumour after chemotherapy." (PMID 22970250, 2012).
tumor (continued). "We show that the impact of GSK3B and CTNNB1 to this signature is not dependent on chemotherapy and more likely reflects a property of the primary tumour and our data further suggest, that in particular NOTCH2 might play a role for chemotherapy resistance in GC." (PMID 22970250, 2012). "However, based on the specific role of Dll4-Notch1 in neovascularization, anti-Dll4, and similarly anti-Notch1 and anti-Notch2 antibodies have been proposed as sharper therapeutic agents devoid of side effects against various tumor types in mouse xenograft models." (PMID 21078177, 2010). "Both NOTCH1 and NOTCH2 were expressed in AFX and PDS tumor cells, and the staining showed mostly a cytoplasmic pattern with or without a nuclear pattern." (PMID 40387567, 2025). "Specifically, miR‐146a‐5p has been reported to bind directly to WNT2, EGFR, NOTCH2, TRAF6, IRAK1 and EIF5A2 to inhibit EMT and act as a tumour suppressor in various human cancers." (PMID 40785027, 2025). "Ultimately, their findings supported a tumour-suppressive function for NOTCH1, and they proposed a similar suppressive role for NOTCH2 and NOTCH3." (PMID 41008920, 2025). "To further explore how the 3D microenvironment in MCP-B hydrogels regulates tumor aggressiveness in HCC, we evaluated the expression of Notch1 and Notch2." (PMID 41149589, 2025). "As a tumor suppressor, BIN1 affects tumor proliferation, metastasis, and stemness through the ALDH1/NOTCH2 pathway." (PMID 40016843, 2025). "In contrast to the tumour suppressor NOTCH1, NOTCH2 and NOTCH3 have demonstrated an oncogenic role in BCa and correlation with poor prognosis." (PMID 41008920, 2025). "High expression of NOTCH2/3 and their ligand DLL4 correlates with increased tumor cell viability and proliferation, suggesting the importance of the NOTCH2/3-DLL4 axis as a potential therapeutic target." (PMID 40635786, 2025). "Inhibition of NOTCH2 or its ligands reversed the EMT phenotype and attenuated the invasive potential of tumor cells." (PMID 41200204, 2025). "Particularly, inhibition of both Notch1 and Notch2 is responsible of GI toxicities observed in both animal models and patients, while Notch2 is required by CD8+ T cells for their anti-tumor cytotoxicity." (PMID 39491031, 2024). "Immunohistochemical analysis using antibodies that recognize active nuclear NOTCH2 in situ supports NOTCH2 activation in SMZL, but shows an expression of NICD2 in both wild-type and NOTCH2 mutant tumours." (PMID 39280243, 2024). "With regard to the other members of the NOTCH gene family, NOTCH2 and NOTCH3 reflected similar expression trends across tumor types." (PMID 39737401, 2024). "The deleted regions contained the tumour suppressors CDKN2C, SDHB, and SFPQ in 1p and CDKN2A in 9p in metastatic samples and the tumour suppressors BCL10 and NOTCH2 and the oncogenes JAK1 and NRAS in 1p in the non‐metastatic sample group." (PMID 37622176, 2023). "In the Notch1 cohort, this appeared to be at the expense of MSCC and AC (NST) phenotypes, whereas in the Notch2 cohort, the AME phenotype tumours were lost, while the MSCC tumours were retained." (PMID 37686600, 2023). "Compared with colorectal T cells from healthy individuals, the expression of PD-1 and Notch signaling molecules (NOTCH1, NOTCH2, HES1, and HES5) was elevated in tumor-infiltrating CD8+ T cells from CRC patients." (PMID 37131214, 2023). "The miR-195-5p/NOTCH2 axis has been reported to induce EMT in CRC cells, which promoted IL-4 secretion to enhance TAMs polarization, thereby promoting tumor progression." (PMID 36841801, 2023). "The results from qRT-PCR analysis showed that the expression of Notch2, NICD, Hes1, and Hey1 in murine tumor tissues from NEDD4L-overexpressed group was significantly decreased compared with control group." (PMID 35646490, 2022).
tumor (continued). "Only six genes were present in both tumor initiation and tumor evolution stage: MUC4, MUC16, USP6, BCLAF1, KMT2C, and NOTCH2." (PMID 34918496, 2022). "Interestingly, Notch2 could play a tumor-suppressive role in human BC." (PMID 35682974, 2022). "Western blot analysis of xenograft tumor tissues confirmed a strong MTA1, Cyclin D1 and Notch 2 downregulation upon treatment with compounds compared to control vehicle-treated tissues." (PMID 33255879, 2020). "Interestingly, we found an enrichment of cluster 4 in tumour of P1207 without NOTCH1/NOTCH2/FBXW7 mutations, but it is not known whether or not P1207 had mutations in other members of the Notch signalling pathway." (PMID 32924269, 2020). "Similar to that in the TKO HCC model, in a delTP53 forebrain glioma tumor mouse, NOTCH1, NOTCH2, or RBJP knockout accelerates tumor progression, in part, by the downregulation of HES5." (PMID 33003595, 2020). "This tumor can be subdivided into a common conventional-type ACC and a solid-type ACC: NOTCH1 (47% vs 7%), NOTCH2 (13% vs 0%), and NOTCH3 (7% vs 0%) were clearly more frequent in solid-type ACC than in conventional-type ACC." (PMID 32210163, 2020). "The result of immunohistochemistry revealed that after the inhibition of SNHG3 expression, Notch1-, Notch2- and Notch3-positive cells in MCF-7 xenograft tumor increased (p < 0.05)." (PMID 32883233, 2020). "Epidermal growth factor-like domain multiple 7 (EGFL7), which modulates Notch2/DLL3 signaling, is involved in regulation of GHoma proliferation and invasiveness, and has been correlated with poor prognosis and tumor grade." (PMID 31508369, 2019). "Conversely, miR-34a experimental induction exerts tumor suppressive effects in CSCs by inhibiting BCL2 Apoptosis Regulator (BCL2) and NOTCH1/NOTCH2 genes and boosting DNA damage responses." (PMID 31450858, 2019). "Exceptions included events private to the primary tumor (SETD2 and ARID1A in LUAD6; NOTCH2 in SCLC1), or private to metastases (SMARCA4 in LUAD5; ARID1A in LUAD7)." (PMID 30348992, 2019). "To further elucidate the carcinogenesis mechanism of miR-1, we first took advantage of bioinformatics software, combined with tumor invasion and metastasis related genes in ESCC, and selected Notch2 as the potential target gene." (PMID 29581534, 2018). "As expected, we found that inhibiting Notch signalling with the γ-secretase inhibitor DAPT also suppressed tumour growth and the expression of CD133 and Notch2." (PMID 30470250, 2018). "In a recent study, we found that anti-Notch2 treatment can reduce both HCC and ICC tumor load induced by AKT and neuroblastoma RAS viral oncogene homolog (NRas) oncoproteins, whereas Notch1 suppression decrease HCC and augments ICC occurrence." (PMID 29545603, 2018). "In summary, our study indicates that Notch2 expression, at least partially, controls BEC fate gene expression in human HCC and ICC tumor cells." (PMID 29545603, 2018). "NOTCH2, a commonly downregulated SMG in the primary tumour data set, was also downregulated in cSCC cell lines in comparison to NHKs." (PMID 30202019, 2018). "Specifically, Notch2 is strongly expressed in ICC cells, whereas Notch1 is predominantly expressed in the cells of the tumor microenvironment." (PMID 29545603, 2018). "What is important is that the treatment of cells with anti-Notch2/3 antibody increased expression of NUMB and significantly reduced the formation of tumor cell spheroids." (PMID 29104587, 2017). "Another point of interest is the elevation in Notch2 and CD274 (PD-L1) expression in a subset of GD2-low tumor cells following P-selectin exposure." (PMID 29156825, 2017). "Among all genes in the focal amplifications, only five (TBX15, NOTCH2, PTGFRN, CNN3, and PHGDH) showed appreciably higher expression levels than those observed in tumor samples from the TCGA database." (PMID 28977029, 2017). "Four SNVs of NOTCH2, PDE4DIP, ATP10B and NSD1 and one frameshift INDEL of BAP1 were validated by Sanger sequencing on tumour RNA." (PMID 28484631, 2017).